COMP (cartilage oligomeric matrix protein)
Diseases named in the same sentence as COMP in open-access papers (continued):
Sharing a sentence is not in itself a finding about the gene and the disease.
Arthritis (continued). "The pathology of arthritis induced by COMP immunization shows similarities with human RA having synovial hyperplasia, increased synovial volume, cellular infiltrates, and the unique feature of a chronic relapsing disease phase with a female preponderance." (PMID 22906101, 2012). "Earlier, we reported that the affinity-purified COMP-specific polyclonal antibodies can induce arthritis in healthy recipients." (PMID 22906101, 2012). "The serum levels of COMP (cartilage oligomeric matrix protein) are elevated in arthritis due to increased destruction of joint cartilage." (PMID 21159208, 2010). "In patients with various types of arthritis, COMP levels were detected in all fluids, but were ten times higher in synovial fluid than in serum indicating preferential release from the affected joints." (PMID 19652761, 2009). "Here, we show that COMP-deficient mice develop an early-onset CIA and more severe arthritis during the chronic phase of the disease." (PMID 19014566, 2008). "The autologous collagen type XI-induced arthritis shows a more aggressive course and pathology, whereas the COMP-induced arthritis is rather acute and self-limited." (PMID 17391515, 2007). "In addition, the CFA + MTX-GNPs gel formula group displayed significant inhibition of COMP by 52.64% compared to the CFA-arthritis group." (PMID 36678557, 2022). "Meanwhile, the concentration of cartilage oligomeric matrix protein (COMP) in the blood may be a candidate indicator of early cartilage lesions in arthritis." (PMID 35662715, 2022). "In addition, the CFA + MTX-GNPs group reported significant inhibition of COMP by 28.16% when compared to the CFA-arthritis group." (PMID 36678557, 2022). "We found that immunization with COMP led to severe arthritis in C57BL/6 mice." (PMID 33708221, 2021). "Both groups immunized with COMP developed severe arthritis with high incidence." (PMID 33708221, 2021). "Serum COMP levels serve as an early biomarker of arthritis and OA." (PMID 33748207, 2021). "Interestingly, in similarity with CII, COMP induces arthritis in mice expressing the murine Aq and the human DR*0401 MHC class II molecules." (PMID 33708221, 2021). "Native COMP was required, as denatured COMP lost its ability to induce arthritis in B6N mice." (PMID 33708221, 2021). "To determine whether phenylalanine at position 95 is critical for the development of arthritis we made a new recombinant COMP protein replacing phenylalanine with serine at position 95 (COMP_F95S)." (PMID 33708221, 2021). "The levels of COMP correlated with arthritis severity in both lpsCAIA and mCAIA." (PMID 32448385, 2020). "In addition, anti-COMP mAbs enhanced arthritis when co-administered with a sub-arthritogenic dose of CII-specific mAb." (PMID 29495570, 2018). "Subsequently, mAbs to COMP were generated and shown to induce arthritis in mice." (PMID 29495570, 2018). "Immunization with COMP leads to induction of arthritis in rats and mice." (PMID 29495570, 2018). "As in RA, the development of arthritis induced by COMP is associated with certain major histocompatibility complex (MHC) haplotypes, indicating that the COMP-induced arthritis (COMPIA) model is dependent on T cell recognition of related peptides presented by appropriate MHC molecules." (PMID 22906101, 2012). "Indeed, combination of single COMP-specific mAbs with a sub-optimal dose of M2139 mAb did induce arthritis." (PMID 22906101, 2012). "Interestingly, we found that a combination of 5 COMP mAbs was capable of inducing arthritis in naive mice." (PMID 22906101, 2012). "Furthermore, arthritis can be transferred from arthritic mice to healthy recipients with affinity purified COMP-specific polyclonal antibodies." (PMID 22906101, 2012).
Arthritis (continued). "Current observations of binding of COMP-specific mAbs directly to the cartilage COMP in its native conformation, and the passive transfer of COMP-specific mAbs leading to arthritis, have important implications for the understanding of the ensuing immune responses against COMP in arthritis." (PMID 22906101, 2012). "This review highlights the progress in the utilization of COMP as a biomarker of arthritis." (PMID 19652761, 2009). "Serum COMP has potential to be used as a biomarker of arthritis." (PMID 19652761, 2009). "The normal time course of COMP and its variations will need to be further delineated before it may be used as a widespread biomarker of arthritis." (PMID 19652761, 2009). "One such potential biological marker of arthritis is cartilage oligomeric matrix protein (COMP)." (PMID 19652761, 2009). "For the female mice, both COMP-deficient and wild-type mice were less susceptible to CIA: only two of eight COMP-deficient female mice developed arthritis, and two of nine wild-type mice developed arthritis." (PMID 19014566, 2008). "The serum COMP level is used as a biomarker both in humans and in experimental animals to detect ongoing inflammation in the joints as well as a measure of severity of the arthritis induced." (PMID 19014566, 2008). "The incidence of arthritis in COMP-deficient male mice (75%) was not significantly different compared with wild-type mice (88.8%)." (PMID 19014566, 2008). "Murine monoclonal anti‐COMP antibody could induce arthritis in naive mice." (PMID 39132510, 2024). "Also, some researchers believe that MSC transplantation could relieve the symptoms of arthritis by downregulating the expression of cartilage oligomeric matrix protein (COMP) on the synovial membrane and in the serum of CIA rats." (PMID 31828174, 2019). "Although COMP has also been identified in smaller amounts in normal ligament, meniscus, tendon, synovium, and osteoblasts as well as in scleroderma skin results from e.g. experimental arthritis clearly indicate that changes in serum levels of COMP in arthritis reflect processes in the cartilage." (PMID 23915292, 2013). "To date, only cartilage binding antibodies, i.e., antibodies to COL2, COMP and G6PI, have been shown to induce arthritis in controlled experiments." (PMID 36754962, 2023). "In the present study, we describe arthritis induced in C57BL/6 mice and identify the key COMP peptide recognized by T cells." (PMID 33708221, 2021). "Interestingly, mice immunized with COMP_F95S could still make a detectable T cell response to COMP protein indicating that the F95S mutation did not abolish all T cell responses, only the T cell response of importance for arthritis development." (PMID 33708221, 2021). "To establish a model for RA in C57BL/6 mice we turned our interest to other proteins that have earlier been shown to induce arthritis in mice, i.e. glucose-6-phosphoisomerase (GPI) and cartilage oligomeric matrix protein (COMP)." (PMID 33708221, 2021). "Only antibodies binding to the cartilage or the cartilage surface (CII, citrullinated CII, CII/CXI, COMP, and G6PI) have so far been shown to induce arthritis in mice." (PMID 32448385, 2020). "High-dose or moderate-dose Bi-Qi treatment, or MTX treatment decreased the arthritis-induced OPN and COMP level in synovium." (PMID 29540195, 2018). "In arthritis research, increased levels of MMP-3, YKL-40 and COMP in the circulation are recognized as biomarkers of cartilage turnover and/or destruction." (PMID 25333960, 2014). "In PsA, integrating biomarkers such as MMP-3, COMP, and genetic factors like HLA-B27 and HLA-C06 improves differentiation between PsA and psoriasis without arthritis." (PMID 40095875, 2025). "In similarity with CIA the induction of arthritis is facilitated by a T cell response to non-self -COMP, due to that the immunodominant peptide is not binding well to the MHC class II molecule and is thus likely to be ignored for development of tolerance." (PMID 33708221, 2021).
Arthritis (continued). "In this study, we show that human COMP, a non-collagen glycoprotein primarily produced by cartilage, can induce arthritis in C57BL/6 mice that carry the H-2b haplotype, which is useful as a model for human RA." (PMID 33708221, 2021). "RA models in rats and mice are most commonly induced by immunization with protein antigen, type II collagen, or homologous cartilage oligomeric matrix protein (COMP) leading to models of antigen-induced arthritis (AIA), collagen-induced arthritis (CIA), or COMP-induced arthritis, respectively." (PMID 33256854, 2020). "In addition, ADAMTS-12 also played a critical role in the pathogenesis of arthritis since ADAMTS-7 and ADAMTS-12 share the common substrate (COMP)." (PMID 26696755, 2015). "The serum COMP-C3b concentration was, however, significantly higher in patients with arthritis than in patients without arthritis, suggesting the importance of joint inflammation and possibly cartilage involvement for the release of complement-activating COMP." (PMID 22264230, 2012). "Specific reagents for degraded COMP are lacking, and therefore have limited the usefulness of this marker to determine the presence of arthritis and to develop an assay with a dichotomous outcome (i.e. normal vs. abnormal for a population)." (PMID 19652761, 2009). "However, COMP alone is not an indicator of OA because other forms of arthritis also direct cartilage breakdown and release of COMP." (PMID 39690934, 2025). "To address whether the chronic development of arthritis in mCAIA could activate an autoantibody response to cartilage proteins, we used a multiplex Luminex test containing known major triple helical CII, CXI, and COMP epitopes." (PMID 32448385, 2020). "There are reports which present COMP as a biomarker in psoriatic patients without arthritis." (PMID 26146462, 2015). "However, SLE patients with arthritis as a part of the disease flare at the time of sampling had significantly higher serum COMP-C3b concentrations than did patients without arthritis." (PMID 22264230, 2012). "SLE patients with arthritis had significantly higher COMP-C3b levels than did those without." (PMID 22264230, 2012). "Indeed, when wild-type and COMP-/- mice, were immunized with COMP, 80% COMP+/+ mice developed severe arthritis, whereas COMP-/- animals exhibited no clinical abnormalities (our unpublished data)." (PMID 22906101, 2012). "COMP deficiency in mice subjected to CIA did not affect either incidence or anti-CII antibody titers but caused a significant early onset and increase in the severity of the disease during the chronic phase of arthritis." (PMID 19014566, 2008). "Using COMP-deficient mice as a negative control and mice immunized with COMP to induce arthritis as a positive control, we investigated whether there was an immune response against COMP during CIA." (PMID 19014566, 2008). "In addition, the cartilage oligomeric matrix protein (COMP)-processing activities of ADAMTS7 and ADAMTS12 were inhibited by α2M, suggesting that dysregulation of the ADAMTS7 and ADAMTS12 protease activity through α2M could be involved in arthritis." (PMID 34268335, 2021). "The elevated COMP levels in the psoriatic patients without arthritis and PsA patients suggest that undetected articular involvement may also be present in psoriatic patients without arthritis." (PMID 26146462, 2015). "In the present study, the observation that COMP-deficient mice show a more severe arthritis during the chronic phase of CIA, but not during the acute phase, supports the hypothesis that COMP is important in cartilage repair processes and thus in cartilage regeneration and remodeling." (PMID 19014566, 2008). "A combination of five selected COMP mAbs, without anti-CII mAb, was also effective to induce arthritis in naïve mice, although with low severity of arthritis." (PMID 22906101, 2012).
breast carcinoma (36 papers, 2011 to 2026). "In breast cancer patients, elevated expression of cartilage oligomeric matrix protein (COMP) is associated with shorter survival and increased metastatic risk." (PMID 41689303, 2026). "We recently showed that COMP mediates the Notch3-Jagged1 interaction, enhancing breast cancer stem cells associated with AKT, PI3K, and β-catenin signaling pathways." (PMID 38615020, 2024). "It has been shown in breast cancer epithelial cells, that COMP is significantly elevated being associated with poor survival, invasiveness, and metastasis." (PMID 36114508, 2022). "Serum COMP is elevated in the advanced breast cancer patients with metastasis and significantly associated with histological subtype, estrogen receptor positivity, and metastasis at diagnosis." (PMID 36012514, 2022). "Previous studies have shown that COMP expression in breast cancer cells is significantly associated with poor prognosis." (PMID 32149116, 2020). "High levels of COMP in sera of metastatic patients were associated with the histological subtype (p = 0.025) and estrogen receptor positivity (p = 0.019) at the time of breast cancer diagnosis." (PMID 31737569, 2019). "Initially, the expression of COMP by breast cancer tumor cells has been associated with poorer prognosis of patients." (PMID 31737569, 2019). "Recently, we showed that breast cancer cells express COMP and that this expression is significantly associated with poor patient survival and an increased rate of metastasis." (PMID 29228690, 2017). "Cartilage oligomeric matrix protein (COMP) was recently implicated in the progression of breast cancer." (PMID 29228690, 2017). "Previously obtained mRNA array data from mice mammary tumors, implicated an effect of COMP on ER stress but also indicated an effect on the TNF receptor 1 (TNFR1) pathway." (PMID 29228690, 2017). "Additionally, it was observed that COMP expression associated with a higher alignment of collagen fibers in breast cancer tumors." (PMID 38563861, 2024). "Similarly, other authors also reported on tissue microarrays from patients that COMP was associated with worse prognosis in breast cancer." (PMID 38892202, 2024). "The mechanisms underlying the effects of COMP in breast cancer progression are under investigation." (PMID 34884987, 2021). "Functionally, COMP promoted increased migration and invasion of breast cancer cells in both autocrine and paracrine manners, dependent on its thrombospondin (TSP) and C-terminal domains." (PMID 41689303, 2026). "Breast cancer cells treated with recombinant COMP or engineered to overexpress COMP exhibited a marked decrease in the epithelial marker CDH1 and an increase in mesenchymal markers such as VIM and VCAN." (PMID 41689303, 2026). "Serum COMP levels were prognostic for survival in patients with breast cancer, colon cancer and hepatocellular carcinoma." (PMID 38563861, 2024). "Lastly, breast cancer patients with tumors expressing COMP, and undergoing chemotherapy or endocrine therapy, exhibited decreased overall survival (OS) in comparison with patients with tumors showing low COMP expression." (PMID 38965233, 2024). "Herein, using in vivo and in vitro experimental approaches, we established that COMP promotes breast cancer cells resistance towards many chemotherapeutic drugs, HER2-targeted therapy, and endocrine therapy." (PMID 38965233, 2024). "COMP has been shown to be upregulated in breast cancer, both in tumor cells and in the stroma, and high expression in tumor cells was an independent factor of shorter survival." (PMID 38563861, 2024). "Breast cancer cells expressing COMP had disengaged caspases -9, -7, and -3, were protected from DNA damage and expressed higher levels of anti-apoptotic proteins, during chemotherapy treatment." (PMID 38965233, 2024).
breast carcinoma (continued). "When the half-maximal inhibitory concentration (IC50) was calculated, we observed that a higher dose of the drugs was needed for breast cancer cell lines expressing COMP to achieve effect similar to the mock cells." (PMID 38965233, 2024). "This study identifies a novel role of COMP in chemoresistance and calpain inactivation in breast cancer, a discovery with potential implications for anti-cancer therapy." (PMID 38965233, 2024). "The current study established that breast cancer cells expressing COMP were resistant to most first-line chemotherapy drugs, the HER-2-targeted drugs, and endocrine therapy drugs." (PMID 38965233, 2024). "Breast cancer patients who received both endocrine therapy and chemotherapy had shorter OS (HR: 2.44, p = 0.0031) when they had tumors expressing high levels of COMP compared to patients with tumors expressing low levels of COMP." (PMID 38965233, 2024). "Collectively, both in vivo and in vitro data demonstrated that COMP expression promotes resistance to therapy in breast cancer cells." (PMID 38965233, 2024). "We previously observed that β-catenin expression was increased in COMP-expressing breast cancer cells, further enhanced by Notch inhibitors." (PMID 38615020, 2024). "Further, COMP expression in cancer cells of breast cancer and intestinal-type periampullary adenocarcinoma was shown to be associated with a shorter overall and recurrence free survival of the patients." (PMID 38615020, 2024). "In this study, we investigated COMP-dependent resistance to chemotherapy in breast cancer and explored its complex molecular mechanisms." (PMID 38965233, 2024). "Higher COMP expression in breast cancer cells reduced ER stress, providing a survival advantage to tumor cells despite high levels of general protein production." (PMID 38965233, 2024). "Previously, we showed that COMP secreted by breast cancer cells promotes the CSC population by activating the Notch3 signaling pathway." (PMID 38615020, 2024). "Recently, COMP was found to be highly expressed in several solid cancer types, including colon, colorectal, prostate, liver, and breast cancer." (PMID 38615020, 2024). "Tumor growth in vivo, and in vitro assays measuring cell survival and apoptosis demonstrated resistance of COMP-expressing breast cancer cells against all studied types of anti-cancer drugs, which are used in clinics as a first or second line of therapy." (PMID 38965233, 2024). "Tumors that developed in a mouse xenograft model, using COMP-expressing breast cancer cells, were resistant to doxorubicin treatment." (PMID 38965233, 2024). "Emerging evidence showed that COMP also promoted breast cancer stem cell induction by activating Jagged1-Notch3 signaling, and accelerated breast cancer metastasis by modulating the metabolic process and metalloprotease-9 (MMP-9) secretion." (PMID 38584705, 2024). "COMP expression by the cancer cells, as well as the levels of COMP in the serum of patients with breast cancer were an independent prognostic factor of patient survival." (PMID 37207219, 2023). "In vivo xenograft models revealed that mice orthotopically inoculated with COMP-expressing breast cancer cells developed larger tumors, and more frequent metastases in the lymph nodes and the lungs compared to mice inoculated with wild-type cells." (PMID 37207219, 2023). "Previous studies have found that COMP can change the biological behaviors and functions of breast cancer cells." (PMID 36012514, 2022). "Emerging evidence shows that COMP plays critical roles in the development of cancerous tumors, including those of breast cancer, colon cancer, and hepatocellular carcinoma." (PMID 35845304, 2022). "Our previous studies in primary breast cancer revealed that COMP expression in breast tumor cells was correlated with reduced breast cancer-specific survival and recurrence-free survival as an independent prognostic marker." (PMID 34884987, 2021).